IL2 (interleukin 2)
Diseases named in the same sentence as IL2 in open-access papers (continued):
Sharing a sentence is not in itself a finding about the gene and the disease.
melanoma (continued). "Together with high-dose interleukin (IL)-2 this treatment has been given to patients with advanced malignant melanoma and impressive response rates but also significant IL-2 associated toxicity have been observed." (PMID 22909342, 2012). "By giving high dose Interleukin 2 it is theorized that it stimulates an immune response against melanoma cells." (PMID 29147288, 2012). "It has also been shown that activated T cells can be supported by transgenic expression of IL-2 in vivo and IL-2 has already been approved for clinical use in patients with metastatic renal-cell carcinoma and malignant melanoma." (PMID 22509395, 2012). "Our results also corroborate recent studies showing the deleterious effect of PGE2 released from mesenchymal stem cells or melanoma-derived fibroblasts on IL-2-induced NK cell activation." (PMID 22253598, 2012). "The first attempt to address at the whole genome level the determinism leading to tumor rejection was an analysis of melanoma metastases biopsied before and after treatment with TA-specific vaccination and concomitant systemic administration of IL-2." (PMID 22576055, 2012). "A total of 47 samples of melanoma invaded LN from stage IIIb melanoma patients treated with TIL plus IL-2 were included in this study." (PMID 23284620, 2012). "SSG was shown by our laboratory to inhibit SHP-1, synergize with IFN-alpha to cure melanoma tumors in mice, and interact with IL-2 in anti-tumor action via a T cell-dependent mechanism." (PMID 22201704, 2011). "We administered four daily doses of DAB/IL2 (12 μg/kg; 2-4 21 day cycles) to a total of 60 stage IV melanoma patients." (PMID 22165955, 2011). "This single-center, exploratory trial demonstrated that DAB/IL2 has significant clinical activity in stage IV melanoma patients." (PMID 22165955, 2011). "The response rate with high-dose intravenous bolus IL-2 is around 25% for metastatic renal cell carcinoma patients, similar to that seen in melanoma patients and with a similar rate of durable complete response in the 7% range." (PMID 24213115, 2011). "In a recently initiated clinical trial of TIL-based ACT, low-dose IL-2, and lymphodepletion preconditioning, one out of five treated melanoma patients has obtained an ongoing partial response (+13 months)." (PMID 21773037, 2011). "High-dose IL-2 induces objective clinical responses in 15–20% of patients with advanced melanoma and durable complete responses in 5–7% of these patients." (PMID 24213115, 2011). "An inflammatory phenotype was also found to be predictive of good outcome in patients with melanoma treated with IL-2 or anti-CTLA-4 mAb." (PMID 21875439, 2011). "We conclude that DAB/IL2 has significant clinical activity in unresectable stage IV melanoma patients." (PMID 22165955, 2011). "The goal of this study was to assess the clinical efficacy of DAB/IL2 in an expanded cohort of stage IV melanoma patients." (PMID 22165955, 2011). "The authors showed that ABCB5+MHC class II+ cells displayed higher capacity than ABCB5- MHC class II-negative melanoma cells to inhibit IL-2-dependent T-cell activation and support the induction of CD4+CD25+FoxP3+ regulatory T cells." (PMID 21526207, 2011). "Based on the results of this study, a new randomized multi-center clinical trial of DAB/IL2 has been initiated that will correlate Treg depletion with objective responses in chemo/immuno-naïve melanoma patients." (PMID 22165955, 2011). "Specific peptide-mediated immunity against established melanoma tumors with dendritic cells requires IL-2 and fetal calf serum-free cell culture." (PMID 21637760, 2011). "Other studies have focused on assessing the number, phenotypic characteristics, and functional status of CD4+FoxP3+ Tregs in melanoma and renal cell carcinoma patients undergoing standard high-dose IL-2 administration." (PMID 24213115, 2011).
melanoma (continued). "The expansion levels reached over 9-11 days of culture using REM and aAPC as performed here in small-scale using extended IL-2 cultured ovarian TILs is less than those levels achieved elsewhere with melanoma TILs over 14 days by REM." (PMID 21827675, 2011). "Single-agent IFN-α and high-dose IL-2 have been approved in the treatment of melanoma and renal cell carcinoma." (PMID 24213115, 2011). "AdCMV-mediated IL-2 expression levels were comparable in the two cell lines tested and reached a minimal 5- to a maximal 12- fold higher levels in melanoma M000301 when compared to TETP-mediated expression levels in these cells." (PMID 20670430, 2010). "As such, IL-2 is a frequent therapy in the treatment of solid tumors, mainly melanoma and renal cancer." (PMID 21059266, 2010). "It is worth noting that NK cells are known to play a major role in cytokine-mediated inhibition of B16 melanoma development and that IL-2 can induce the proliferation and activity of NK cells." (PMID 20856939, 2010). "Treatment for both early and advanced melanoma has changed little since the introduction of interferon and IL-2 in the early 1990s." (PMID 20406483, 2010). "Clinical trials in the management of melanoma have shown that some cytokines are beneficial and have anti-neoplastic effect such as interferon α-2b and interleukin-2." (PMID 24281094, 2010). "Here we intended to restrict Ad-mediated expression of immunotherapeutic CD40L and IL-2 genes to melanoma cells by replacing the CMV promoter of a first-generation, E1/E3-deleted Ad5-based vector with the melanoma/melanocyte-specific TETP." (PMID 20670430, 2010). "Melanoma patients with high serum IL-6 have a shorter survival and a tendency to be resistant to IL-2 therapy." (PMID 24281094, 2010). "All but 6 patients had received prior systemic therapy for melanoma, and 27 (75%) had previously received the cytokines IFNα2 or interleukin-2 (IL2) alone or in combination with chemotherapy." (PMID 20109236, 2010). "Chemotherapy (e.g. dacarbazine) and cytokine adjuvant therapy (e.g. high-dose IFN-α2b and IL-2) are commonly used as a palliative systemic therapy in patients with advanced melanoma." (PMID 20856939, 2010). "Adoptive cell transfer of tumor infiltrating lymphocytes to lymphodepleted patients with melanoma in combination with high dose IL-2 has been shown to achieve clinical responses in the range of 50%." (PMID 19175928, 2009). "In melanoma-bearing mice treated with cisplatin, HemoHIM administration also increased the activity of NK cells and Tc cells and the IL-2 and IFN-γ secretion from splenocytes, which seemed to contribute to the enhanced efficacy of cisplatin by HemoHIM." (PMID 19292900, 2009). "Conversely, those treated with high-dose interleukin-2 (IL-2) for melanoma and renal cell carcinoma show expansion of these cells." (PMID 19277040, 2009). "A similar increase in Treg number and function occurred when patients with RCC and melanoma were treated with IL-2." (PMID 19384299, 2009). "IL-2 plays an important role in T-cell biology and is effective in the treatment of certain cancers, such as RCC and melanoma, where it is associated with increased effector T-cell responses." (PMID 19384299, 2009). "IL-2 regimens have been tested in several types of cancers, with a 15% response rate only in human metastatic renal cell carcinoma and melanoma." (PMID 19175928, 2009). "In a second study, twelve stage IV melanoma patients were administered DAB/IL2 at a lower dose (9 μg/kg) and a higher dose (18 μg/kg) daily × 5 days every three weeks." (PMID 18334033, 2008). "We administered DAB/IL2 (12 μg/kg daily × four days) to stage IV melanoma patients and measured the peripheral blood concentration of lymphocytes, granulocytes and monocytes on days 0, 1, 2, 3, 4, 7 and 21 using an automated hematology analyzer (n = 10)." (PMID 18334033, 2008).
melanoma (continued). "Sixteen heavily pre-treated stage IV melanoma patients were administered 1–4 cycles of DAB/IL2 (12 μg/kg daily × four days every 3 weeks)." (PMID 18334033, 2008). "This single site, investigator-initiated phase II clinical trial has been expanded to provide further evidence for the efficacy of DAB/IL2 against melanoma." (PMID 18334033, 2008). "Sixteen patients received at least one cycle of DAB/IL2 and five of these patients experienced regressions of melanoma metastases as measured by CT and/or PET imaging." (PMID 18334033, 2008). "The signatures identified by both studies also match the anecdotal identification of the same genes in a melanoma metastasis that underwent regression following systemic IL-2 therapy." (PMID 17222352, 2007). "In fact, a recent clinical study on renal cancer and melanoma utilizing a DNA methylation inhibitor along with high-dose interleukin-2 achieved encouraging response rates attributed to facilitation of the immune response against the tumor." (PMID 17183730, 2006). "Antigen-specific T cells isolated directly from tumour biopsies (tumour infiltrating lymphocytes (TILs)) are identified by observing their functional response against melanoma antigens and then subsequently expanded ex vivo by IL-2-driven expansion regimes." (PMID 16251873, 2005). "It is not a controlled clinical trial; it is rather observations that nevertheless can shed some light on the clinical value of combining autologous melanoma vaccine with IL-2." (PMID 14970852, 2004). "Here, we present the results of a study investigating the feasibility, efficacy, and safety of intralesionally injected IL-2 in 24 melanoma patients with skin and soft-tissue metastases." (PMID 14583759, 2003). "The low level of expression of T-cell signal transduction molecules in TIL-1 and the increase produced by in vitro culture in the presence of IL-2 were observed in both melanoma and colorectal carcinoma patients." (PMID 12610520, 2003). "The expression of T-cell transduction signals and apoptosis markers was analysed in TIL before (TIL-1) and after (TIL-2) in vitro culture with IL-2 in 20 patients with advanced melanoma and in 16 with advanced colorectal cancer." (PMID 12610520, 2003). "After IL-2 culture in melanoma TIL, high levels of Fas and Bax and low Bcl-2 expression were observed." (PMID 12610520, 2003). "In conclusion, our study has documented the feasibility of intralesional IL-2 therapy in melanoma patients with skin and soft-tissue metastases." (PMID 14583759, 2003). "To correct the expected lymphocytopenia by TMZ in such an immunogenic tumour as malignant melanoma, we administrated combined immunotherapy with GM-CSF, low-dose IL2 and IFNα s.c. for 12 days in a dosing schedule determined in a phase I study." (PMID 12610499, 2003). "Similar patterns of restored activation molecules after IL-2 culture were observed in melanoma and colorectal carcinoma TIL." (PMID 12610520, 2003). "Further phase III trials with continuous infusion and higher dosages must be performed before any final conclusions can be drawn on the potential usefulness of IL-2 in biochemotherapy of advanced melanoma." (PMID 11308250, 2001). "Our data indicate that B7.1- and B7.2-transduced melanoma cells trigger lymphocytic proliferation with transcription of IL-10, IL-2 and IFN-gamma." (PMID 9652756, 1998). "Peripheral blood lymphocytes (PBLs) from 14 patients with stage III melanoma were isolated and incubated in the presence of 1,000 U ml-1 IL-7 and 100 U ml-1 IL-2 for comparison." (PMID 8018541, 1994). "In two patients, IL-7-induced LAK-cell activity against autologous melanoma cells exceeded even that of IL-2 significantly (67% vs 35% and 95% vs 82%)." (PMID 8018541, 1994). "Recombinant interleukin-2 (rIL-2) therapy has been shown to be of value in the treatment of some cases of melanoma and renal cell carcinoma." (PMID 8431359, 1993).
melanoma (continued). "Serum-free supernatants from in vitro maintained gastrointestinal cancer and melanoma cell lines inhibit the generation of lymphokine (IL-2) activated killer (LAK) cells in a time and dose-related manner." (PMID 2785396, 1989). "Recombinant interleukin-2 (rIL-2) was used to treat 31 patients with progressing metastatic malignant melanoma." (PMID 2803954, 1989). "Administration of different amounts of IL-2 in vivo to 2 patients with melanoma revealed that the initial level of IL-2 in the circulation was related to the dose given and had a half-life of approximately 22.5 minutes." (PMID 6600395, 1983). "Additionally, anti-IL-20R2 treatment reduced the expression of IFNγ, GZMB, IL-2, and TNFα in Jurkat cells co-cultured with Vin-treated melanoma cells." (PMID 40866941, 2025). "A pivotal phase III clinical study (NCT00019682) has demonstrated that in patients with advanced melanoma, the concurrent administration of the gp100 vaccine along with interleukin-2 can enhance response rates and extend PFS when compared to the use of interleukin-2 as a monotherapy." (PMID 39861694, 2025). "Additionally, interleukin-2 (IL-2) (Aldesleukin, a recombinant form of IL-2) has been used to treat metastatic renal cell carcinoma and melanoma." (PMID 41301547, 2025). "In melanoma, IL-2 plays a role in shaping the antitumor immune response and modulating the tumor microenvironment (TME), which may contribute to immune suppression." (PMID 40636453, 2025). "Thus, the full potential of targeting the IL2 pathway for the treatment of advanced melanoma remains to be exploited." (PMID 39895413, 2025). "In melanoma-bearing mouse models, fusion of IL-2 with an antibody specific for GD2 inhibited lung and liver metastases and prolonged survival following lymphokine-activated killer (LAK) cell reconstitution in immunocompromised mice, compared to unconjugated IL-2 administration." (PMID 41568361, 2025). "This prospective single-center study examined associations between serum cytokines—TNF-α, IL-2, and IL-10—and outcomes in stage IV non-small cell lung cancer (NSCLC, n = 43) and melanoma (n = 15) patients treated with Nivolumab at the Oncology Institute in Cluj-Napoca, Romania." (PMID 41020868, 2025). "For instance, Interleukin-2 (IL-2) is approved for treating metastatic renal cancer and advanced melanoma, while interferon-alpha (IFN-α) is utilized to treat patients with conditions like AIDS-related Kaposi sarcoma, hairy cell leukemia, chronic myeloid leukemia, and follicular lymphoma." (PMID 40768059, 2025). "Although IFN-α2b and high dose IL-2 therapy showed potential in improving prognosis in earlier clinical trials, many melanoma patients were unable to continue these treatments due to severe toxicities, such as fatigue, fevers, arthralgias, liver function abnormalities, neutropenia, and nausea." (PMID 40647561, 2025). "Distinct patterns of immune activation and regulation are evident between cancer types, with melanoma patients generally exhibiting stronger pro-inflammatory responses (e.g., IL-2 and TNF-α elevations), while IL-10 dynamics suggest differential regulatory feedback." (PMID 41020868, 2025). "Notably, orthogonal IL-2-IL-2R pairs demonstrated efficacy with minimal toxicity in a murine melanoma model." (PMID 40612864, 2025). "Research analyzing IL-2 levels in melanoma patients found that serum sIL-2R concentrations were notably higher than in healthy individuals, with elevated levels consistently present throughout all stages of melanoma." (PMID 40636453, 2025). "Moreover, TILs treatment requires pre-chemotherapy plus high-dose interleukin-2 (IL-2) (high side effects), and efficacy is limited to few tumors (e.g., melanoma and cervical cancer)." (PMID 40972581, 2025). "In contrast, melanoma patients demonstrated marked and sustained IL-2 elevations, particularly by six months, which may be compatible with more robust T-cell activation, though our small sample size limits firm conclusions." (PMID 41020868, 2025).
melanoma (continued). "Similarly, in the B16 melanoma model, localized delivery of liposomal IL-2 into tumors promoted CD3+ T-cell infiltration and provided systemic defense against secondary tumors." (PMID 40143046, 2025). "A comprehensive review of multiple clinical trials examining peptide vaccines for melanoma demonstrated that the addition of IL-2 to peptide vaccines could enhance disease control in patients, as compared to IL-2 alone." (PMID 40746887, 2025). "IL-2 and IL-15 are cytokines known for their immune-boosting properties, which are significant in melanoma treatment, particularly in modulating immune responses in regional lymph nodes (LNs), a common site for early melanoma metastasis." (PMID 40636453, 2025). "TILs are endogenous, polyclonal lymphocytes harvested from resected tumors, expanded in interleukin-2, and reinfused following lymphodepletion—capitalizing on the natural breadth of tumor antigen recognition and showing long-lasting responses in melanoma and other solid cancers." (PMID 40981188, 2025). "Likewise, a viral melanoma vaccine plus high-dose IL-2 immunotherapy yielded only a 12.5% partial response rate (with responses confined to the IL-2–augmented arm)." (PMID 41150456, 2025). "On the other hand, an increased CD57+CD27+ CD8 T subset among melanoma TIL could proliferate in response to IL-2 and differentiate into CD57+CD27– T with increased perforin expression and potent anti-tumor cytotoxicity." (PMID 40868094, 2025). "An engineered IL-2–based cytokine, such as nemvaleukin, appears promising for melanoma treatment." (PMID 40636453, 2025). "The same study reported that resveratrol also acted synergistically with interleukin-2(IL-2) to increase these antitumor effects, indicating resveratrol’s promising use for boosting NK cell activity in fighting tumor growth and metastasis in melanoma." (PMID 41463545, 2025). "Recent Phase II and III trials have evaluated various combinations of IL-2 therapies for melanoma." (PMID 40636453, 2025). "IL-2, in particular, was the pioneering immunotherapy to exhibit significant antitumor efficacy, with patients demonstrating complete and durable responses in melanoma and renal cell carcinoma." (PMID 38903504, 2024). "Studies have also demonstrated that the overall objective response rate may be improved by combining IL-2 treatment with melanoma vaccines." (PMID 39682188, 2024). "A study carried out as early as 1988 showed that immune cells extracted from melanoma patients could mediate the objective regression of melanoma in some patients after expansion in vitro, combination with IL-2 and infusion back into the patient." (PMID 38254219, 2024). "Moreover, preclinical and clinical studies have demonstrated that IL-2 can augment the development of immune cells, enhancing their abilities to eliminate cancer cells, particularly in renal cell carcinoma and malignant melanoma." (PMID 39317690, 2024). "In addition, NK cells, CD8 + T cells, and T helper cells secrete cytokines like IFNγ, tumor necrosis factor (TNF), and IL-2, preventing tumor growth and angiogenesis in a melanoma and a pancreatic cancer mouse model." (PMID 38419052, 2024). "NK cell activity is impaired in advanced melanoma, so the combination of IL-2 and IL-12 may be a promising combination strategy in the advanced melanoma treatment by improving NK cell function." (PMID 38753073, 2024). "Various immunotherapies were studied in the review coordinated by Teulings, including general stimulation with interferon-α (IFN- α) or interleukin-2 (IL-2), a modified oncolytic virus, and immune check-point inhibitors, the last being the standard immunotherapy for melanoma nowadays." (PMID 39421737, 2024). "Furthermore, injection of MSCs expressing IL-2 into B16 melanoma-bearing animals suppressed tumour progression by CD8 and NK cells but not by the activation of CD4 cells." (PMID 39416732, 2024).